KCNH7 (potassium voltage-gated channel subfamily H member 7)
Description:
Pore-forming (alpha) subunit of voltage-gated inwardly rectifying potassium channel. Exhibits faster activation and deactivation kinetics and slow inactivation at membrane potentials positive to 240 mV, resulting in the weakest inward rectification.
Synonyms: ERG3; Kv11.3; HERG3
Tractability: Small molecule: an approved drug acts on it; it belongs to a druggable protein family. Antibody: its Gene Ontology location is reachable by antibodies, with high confidence; UniProt places it where antibodies can reach, with medium confidence; UniProt predicts a signal peptide or a membrane-spanning region.
Gene: Protein-coding gene on chromosome 2 (162,371,407 to 162,838,767, reverse strand). Ensembl gene ENSG00000184611.
Subcellular location: Cell membrane
Pathways (Reactome):
Neuronal System: Voltage gated Potassium channels
Gene Ontology:
Molecular function: heme binding; inward rectifier potassium channel activity; monoatomic ion channel activity; voltage-gated potassium channel activity
Biological process: potassium ion transport; potassium ion transmembrane transport; regulation of membrane potential; monoatomic ion transport; transmembrane transport
Cellular component: plasma membrane; membrane
Genetic constraint (gnomAD): Loss-of-function variants: 42 observed, 109.17 expected, observed/expected ratio (o/e) 0.38, 90% interval 0.3 to 0.5. The upper end of that interval is the gene's LOEUF score, 0.5, which puts it in group 2 of 6, group 1 being the genes least tolerant of losing a copy. Missense variants: 1,039 observed, 1,438.2 expected, observed/expected ratio (o/e) 0.72, 90% interval 0.69 to 0.76. Synonymous variants: 523 observed, 514.89 expected, observed/expected ratio (o/e) 1.02, 90% interval 0.94 to 1.09.
Homologues: Orthologues: chimpanzee KCNH7 (99% identical), rabbit KCNH7 (96% identical), pig KCNH7 (96% identical), dog KCNH7 (96% identical), mouse Kcnh7 (94% identical), rat Kcnh7 (94% identical), guinea pig KCNH7 (93% identical), macaque KCNH7 (84% identical), tropical clawed frog kcnh7 (81% identical), zebrafish kcnh7 (66% identical), Caenorhabditis elegans unc-103 (36% identical), Drosophila melanogaster sei (34% identical), and 9 more. Paralogues in human: KCNH2 (57% identical), KCNH6 (49% identical), KCNH8 (30% identical), KCNH4 (30% identical), KCNH5 (28% identical), KCNH1 (27% identical), KCNH3 (27% identical), HCN4 (15% identical), HCN2 (14% identical), HCN1 (13% identical), HCN3 (13% identical), CNGA1 (12% identical), and 5 more.
Diseases named in the same sentence as KCNH7 in open-access papers:
KCNH7 is named in the same sentence as 23 diseases in open-access papers, as found by Europe PMC text mining. Sharing a sentence is not in itself a finding about the gene and the disease. The quoted sentences say what the papers report.
bipolar disorder (4 papers, 2014 to 2025). A disorder of the brain that causes unusual shifts in mood, energy, activity levels and the ability to carry out day-to-day tasks. "Variants of KCNH7 were associated with a wide range of neuropsychiatric disorders, including developmental delay, bipolar disorder and schizophrenic psychoses." (PMID 37542675, 2023). "Association at the KCNH7 locus with bipolar disorder was also reported at rs6736615, an intronic variant, in a recent case-control study of 400 Taiwanese subjects." (PMID 24625924, 2014). "Studies have demonstrated the association between KCNH7 and bipolar disorder and autism." (PMID 31543842, 2019). "Among Kv channels, KCNQ2, KCNQ3, and KCNH7/Kv11.3 have been identified as candidate genes for bipolar disorder." (PMID 40334257, 2025). "Further studies are needed to investigate the pharmacogenetic relationships between KCNH7 and risperidone in bipolar disorder and autism, and the possible role of KCNH7 in the treatment efficacy of risperidone in bipolar disorder remains to be investigated." (PMID 31543842, 2019). "The authors would also like to thank Kevin Strauss and Erik Puffenberger for sharing data on the analysis of KCNH7 in bipolar disorder." (PMID 24625924, 2014).
epilepsy (2 papers, 2023 to 2025). A brain disorder characterized by episodes of abnormally increased neuronal discharge resulting in transient episodes of sensory or motor neurological dysfunction, or psychic dysfunction. "In summary, our study provides evidence supporting that the KCNH7 gene is a candidate gene in pediatric epilepsy, and different domains affected by various mutations may be correlated with the severity of symptoms in patients." (PMID 39634124, 2025). "Functional study of the KCNH7 gene provided evidence to support its association with epilepsy." (PMID 39634124, 2025). "We are currently conducting relevant functional validation studies to further demonstrate the correlation between the KCNH7 gene and epilepsy." (PMID 39634124, 2025). "This association provided a foundation for further experimental and clinical investigations, contributing to the confirmation of the precise role of the KCNH7 gene in the etiology of epilepsy." (PMID 39634124, 2025). "Collectively, these findings suggested a potential role of the KCNH7 gene in epilepsy." (PMID 39634124, 2025). "However, until our study, there were limited clinical cases linking the KCNH7 gene to epilepsy." (PMID 39634124, 2025).
autism spectrum disorder (1 paper, 2019). A spectrum of developmental disorders that includes autism, and Asperger syndrome. "Targeted massively parallel sequencing demonstrates a nominal gene-based rare variant association between autism spectrum disorder and KCNH7 (P = 0.043)." (PMID 31543842, 2019).
deafness (1 paper, 2023). An inherited or acquired condition characterized by the complete loss of the ability to hear from one or both ears. "In addition, two LLN genes are expressed in critical loci associated with deafness, Kcnh7 in DFNA16 and Tmem215 in DFNA47." (PMID 36999169, 2023).
emotional dysregulation (1 paper, 2023). "We identified several molecular markers, including Dgkh, Arfgef3, Kcnh7, Grin2a, Tenm1 and Epha6, implicated in neurodevelopmental deficits and psychiatric conditions featuring impaired cognition and emotional dysregulation." (PMID 37542675, 2023).
influenza (1 paper, 2019). An acute viral infection of the respiratory tract, occurring in isolated cases, in epidemics, or in pandemics; it is caused by serologically different strains of viruses (influenzaviruses) designated A, B, and C, has a 3-day incubation period, and usually lasts for 3 to 10 days. "Furthermore, RNAseq identified altered expression of ART3 and KCNH7 genes that were not previously detected in influenza transcriptomes." (PMID 31461941, 2019).
mental disorder (1 paper, 2019). A disease that has its basis in the disruption of mental process. "KCNH7 might be an important genetic factor in the efficacy of risperidone against mental disorders." (PMID 31543842, 2019).
schizophrenia (1 paper, 2019). A major psychotic disorder characterized by abnormalities in the perception or expression of reality. "Here, we assessed the genetic association of KCNH7 with risperidone responses in 393 schizophrenia patients." (PMID 31543842, 2019). "To this end, we performed a pharmacogenetics association study to identify the genetic function of KCNH7 and examined the associations between the KCNH7 genotype and risperidone efficacy in schizophrenia patients of Han Chinese ancestry over a 6-week acute treatment." (PMID 31543842, 2019). "The findings indicate that the voltage-gated K+ channel KCNH7 is a potential functional marker for the identification of the response to risperidone treatment in schizophrenia patients." (PMID 31543842, 2019). "Accordingly, the biological effect of KCNH7 on the efficacy of risperidone treatment in schizophrenia has been added to our study agenda." (PMID 31543842, 2019). "In this study, we hypothesized that KCNH7 contributes to the outcomes of risperidone treatment in schizophrenia patients." (PMID 31543842, 2019). "Moreover, studies on the difference in regulation and effects between KCNH7 and KCNH2 will help understand the function of the Kv channel in schizophrenia." (PMID 31543842, 2019).
neurodevelopmental disorder (1 paper, 2025). A behavioral and cognitive disorder with onset during the developmental period that involves impaired or aberrant development of intellectual, motor, or social functions. "Likewise, the transcriptional activator AUTS2, KCNH7 potassium channel variants, lysine methyltransferase SETD2 (which is also downregulated in mice), and USP7, among others, are induced by rest, and their mutations are associated with a variety of neurodevelopmental disorders." (PMID 40725218, 2025).
tumor (1 paper, 2025).
KCNH7 also shares sentences with these, for which no sentence is quoted: breast carcinoma (3 papers); cancer (2); autism (1); brucellosis (1); cardiac ischemia (1); cholera (1); developmental delay (1); esophageal squamous cell carcinoma (1); heart disease (1); infection (1); melanoma (1); Obesity (1); psychosis (1).